RNU6-86P (RNA, U6 small nuclear 86, pseudogene)
Gene: Small nuclear RNA gene on chromosome 9 (87,998,229 to 87,998,335, reverse strand). Ensembl gene ENSG00000271923.
Homologues: Orthologues: chimpanzee U6 (100% identical), mouse Gm25473 (93% identical), mouse Gm23714 (88% identical). Paralogues in human: RNU6-774P (93% identical), RNU6-11P (93% identical), RNU6-28P (93% identical), RNU6-37P (93% identical), RNU6-21P (92% identical), RNU6-38P (92% identical), RNU6-560P (92% identical), RNU6-1 (91% identical), RNU6-2 (91% identical), RNU6-33P (91% identical), RNU6-39P (91% identical), RNU6-3P (91% identical), and 1284 more.